CXCL13 (C-X-C motif chemokine ligand 13)
Diseases named in the same sentence as CXCL13 in open-access papers (continued):
Sharing a sentence is not in itself a finding about the gene and the disease.
melanoma (continued). "CXCL13 was suggested as a prognostic biomarker in melanoma before, but the correlation of ERCC3 with survival needs further validation." (PMID 35174087, 2022). "Gene profiling of human melanomas identified CXCL13 and IL-8 as components of a smaller group of 12 genes found to be diagnostic markers from a larger 200-gene signature." (PMID 24762633, 2014). "The formation of TLS in melanoma is likely to be CXCL13-mediated, as in breast and colon cancer, although melanoma immune response literature is currently T cell-focused." (PMID 24762633, 2014). "Other microarray datasets studied in melanoma implicate IL-8, CXCL13, IRF1, IRF2 and IL-12 as possible prognostic markers." (PMID 24762633, 2014). "CXCL13 was strongly expressed in a minor subpopulation of tumor cells in primary melanoma, while a greater fraction of cells in metastatic melanoma tissue expressed this protein." (PMID 23638386, 2013). "Third, we validated the expression of MAPK-associated members (COL11A1, CXCL13, PTPRF, SHC4) of the 12-gene biomarkers in a comparative analysis of normal melanocytes and melanoma cells in vitro and in primary versus metastatic melanoma biopsy tissue in situ." (PMID 23638386, 2013). "While SHC4 has been reported previously to be associated to melanoma, this is the first time CXCL13, COL11A1, and PTPRF have been associated with melanoma on experimental validation." (PMID 23638386, 2013). "To further understand how CXCL13 enhances the invasiveness and immune evasion capabilities of melanoma cells, we examined the protein levels in melanoma cells after CXCL13 treatment and observed a significant upregulation of matrix metallopeptidase 9 (MMP9) and programmed death‐ligand 1 (PD‐L1)." (PMID 40692663, 2025). "Notably, in both NSCLC and Melanoma, there is an increase in the proportion of CXCL13+ T cells in the TME following anti-PD-1-treatment, which lack markers of terminal exhaustion displaying a phenotype of T-exhausted precursor cells (Texp)." (PMID 37520560, 2023). "Intriguingly, the CXCL13+ CD8-Tterm.ex population was most prominent in melanoma BrM." (PMID 37655659, 2023). "Indeed, we found B cell chemokine CXCL13 was required to generate optimal anti-melanoma effect and prolonged mouse survival in response to combination therapy with anti-PD-L1 plus TLR-7/8." (PMID 35720386, 2022). "This assumption might explain that in our analysis, CXCL13 expression, as a specific marker of exhausted T cells, was only prognostic in melanoma tissue of older when subdividing by patient age." (PMID 35174087, 2022). "In addition, melanoma patients’ TCGA data showed that the presence of B cell chemokine CXCL13 and B cells together with CD8+ T cells in tumors were strongly associated with improved overall survival." (PMID 35720386, 2022). "Furthermore, our findings showed that combination therapy with anti-PD-L1 antibody and TLR-7/8 agonist also required CD40 positive B cells and their chemokine CXCL13 to generate optimum anti-melanoma immunity." (PMID 35720386, 2022). "Moreover, we also found that the high expression levels of CXCL13, FCRLA, MS4A1, and PLA2G2D were positively associated with the better response of melanoma patients treated with anti-PD1 and anti-CTLA4." (PMID 34395521, 2021). "Furthermore, in vitro cytotoxicity assays revealed that the inhibitory effect of CXCL13 on melanoma cells in PBMCs could be reversed, with even 50 ng/mL CXCL13 completely reversing the PBMC‐mediated killing of melanoma cells." (PMID 40692663, 2025). "Like melanoma, MANA-specific TIL in NSCLC showed higher expression of CXCL13 and ENTPD1, and lower expression of IL7R compared with virus-specific TIL." (PMID 39900903, 2025). "Chemokines like CXCL13 in the TME influence B-cell infiltration and the formation of tertiary lymphoid structures (TLSs), which correlate with better survival rates in melanoma patients." (PMID 40636453, 2025).
melanoma (continued). "Using Pf4 Cx3cr1 mice to deplete CD206hi IMs expressing Cxcl13, Cxcl9, and Cxcl10, we demonstrate their essential role in TLS formation, lymphocyte recruitment, and tumor suppression in melanoma and lung adenocarcinoma." (PMID 40630529, 2025). "Exhausted T cells within melanoma tumors also produce CCL4 and CXCL13, which in turn recruit other relevant immune cells from the circulation such as dendritic or B cells, potentially resulting in tertiary lymphoid structures." (PMID 38562921, 2024). "Additionally, the presence of inflammatory (CXCL-11) and lymphoid (CXCL-13) chemokines has been associated with the recruitment of tumor infiltrating lymphocytes, namely CD4+ T cells, CD8+ T cells and mature dendritic cells, to promote melanoma cell destruction." (PMID 38812776, 2024). "In an exploratory fashion, we further studied melanomas from 5 patients with coordinately elevated serum levels of TNFSF13 and CXCL10 or CXCL13." (PMID 37435077, 2023). "We utilized the qRT-PCR method to explore CCL8, CXCL13 and IRF4 expression level in melanoma A375 cell lines and HFB4 control cell line." (PMID 38155221, 2023). "For other chemokines, most of them tended to express higher in FGFR Mut melanoma, such as CCL5, CCL19, CXCL9, CXCL10, CXCL11, CXCL13 and CXCL14 (all P > 0.05)." (PMID 36426352, 2022). "TGF-β-expressing B cells in the melanoma tumor microenvironment assembled in clusters and interacted with T cells via lymphoid recruitment (SELL, CXCL13, CCL4, CD74) signals and with Tregs via CD47:SIRP-γ, and FOXP3-promoting Galectin-9:CD44." (PMID 35909944, 2022). "TLS co-infiltrating CD8+ T cells and CD20+ B cells enhanced survival in metastatic melanomas co-expressing CXCR5 and CXCL13, whereas B-cell-enriched melanomas were accompanied by increased levels of naive or memory T cells." (PMID 35563678, 2022). "Our results showed that the CXCL13, FCRLA, MS4A1, and PLA2G2D were positively correlated with the level of CTL infiltration in the melanoma patients treated with anti-PD-L1 or anti-CTLA4." (PMID 34395521, 2021). "Increased glycolysis (melanoma: p<0.0001; NSCLC: p<0.0001) and secretion of CXCL13 were found in (melanoma: logFC=1.22, p.adj<0.0001; NSCLC: logFC=0.85, p.adj<0.0001) PD-1hiCD8+ T cell, consistent with a previous report." (PMID 34604032, 2021). "Collectively, we conclude that IL-33 catered by Cxcl13-Cre+ FSCs to CD8+ T cells in the TME sustains T cell effector differentiation and prevents T cell exhaustion, hence enabling curative melanoma treatment by LCMV-based viral vectors." (PMID 34354077, 2021). "Logistic regression revealed that the key genes responsible for these results were CXCL9 and SPP1 for melanoma and IL6 and CXCL13 for LSCC." (PMID 32383556, 2020). "COL11A1, CXCL13, PTPRF, and SHC4 were found to be over-expressed in two human melanoma cell lines (i.e., FM55 and FM94) compared to normal human epidermal melanocytes in vitro." (PMID 23638386, 2013). "Importantly, the majority of MANA-specific TIL resided in similar TRM clusters in both cancers (84.62% for NSCLC and 59.78% for melanoma), characterized by expression of CD103, CXCL13, ZNF683, and ENTPD1 (CD39)." (PMID 39900903, 2025). "The melanoma immunotherapy dataset PRJEB23709(n=91), GSE100797(n=25), GSE78220(n=28), GSE91061(n=109), Nathanson_2017(n=24), phs000452(n=153) were included to analyze the influence of DUSP1, CXCL13, SLAMF7 and EVI2B in immunotherapy response." (PMID 39687627, 2024). "In melanoma patients, for example, intratumoral-tumor reactive T cells showed increased expression of exhaustion markers, reduced IFN-γ production and increased CXCL13 production compared to circulating tumour reactive T cells (as identified by tetramer staining)." (PMID 37520560, 2023). "Our work revealed that serum level of APRIL/TNFSF13, but not CCL19, CXCL10 or CXCL13 when considered as single analytes, was associated with improved event-free survival (EFS) in patients with melanoma." (PMID 37435077, 2023).
melanoma (continued). "In the melanoma sample (patient 16), CXCL9, CXCL10, CXCL11, and CXCL13 as well as tumor growth factor beta (TGF-β) were higher at the tumor periphery, indicating that T cells in this region are subject to a unique chemokine and cytokine milieu compared with those deeper within the tumor." (PMID 35584630, 2022). "B cell infiltration into colorectal and breast cancers requires CXCL13, but to our knowledge, no previous studies have addressed this in melanoma." (PMID 34454518, 2021). "The over-expression of COL11A1, CXCL13, PTPRF, and SHC4 in melanoma cells in vitro and in situ may reflect the observed over-expression of the associated genes in our microarray meta-analysis results." (PMID 23638386, 2013). "Similarly, a weak cytoplasmic localization of CXCL13 in normal melanocytes appeared to shift towards the perikayon and nucleus of FM55 and FM94 melanoma cells respectively, as evidenced by co-localization with DAPI staining." (PMID 23638386, 2013). "Note that COL11A1, CXCL13, and PTPRF have not previously been reported to be associated with melanoma experimentally." (PMID 23638386, 2013). "Similarly, knockout mouse studies have demonstrated a notable decrease in lung metastasis of melanoma in the absence of CXCL13." (PMID 39344390, 2024). "Hence, this small pilot study supports a paradigm for studying expression of a 3 TLS-kine index (APRIL/TNFSF13, CXCL10 and CXCL13) in serum that may predictive presence of histologically defined LA and/or TLS in the TME of melanoma patients." (PMID 37435077, 2023). "The CXCL13/CXCR5-axis, with its prominent role in launching adaptive immune responses and its circulating soluble and cellular components, could be an additional promising resource for anti-cancer biomarker research in immunogenic tumors, such as melanoma." (PMID 36836910, 2023). "Additionally, our study showed that non-responding melanomas were enriched with B-cells, and they exhibited higher expression of chemokine C-X-C motif ligand 13 (CXCL13) (p value = 0.02, Mann-Whitney U), compared to responding melanomas." (PMID 36248850, 2022). "The over-expression of COL11A1, CXCL13, PTPRF and SHC4 in our melanoma cell lines and primary and metastatic tissue, and their potential association with MAPK pathways suggests they could be specific biomarkers for melanoma and so potential therapeutic targets." (PMID 23638386, 2013). "Studies have shown that the presence of CXCL13+ CD4+ T cells and CXCL13 expression broadly correlates with OS in a cohort of melanoma patients, independent of immunotherapy type." (PMID 37900283, 2023). "In the melanoma cohort, PD-1 blockade responders (R) had significantly higher enrichment scores for the CD4+_MKI67 signature (p = 0.025) and the CD4+_CXCL13 signature (p = 0.05) than nonresponders (NR) did, indicating the predictive value of this cell population." (PMID 38383773, 2024).
lymphoma (44 papers, 2010 to 2025). A malignant (clonal) proliferation of B- lymphocytes or T- lymphocytes which involves the lymph nodes, bone marrow and/or extranodal sites. "The DDF cluster was of particular interest, given its association with the highest prevalence of lymphoma and increased levels of C-X-C motif chemokine ligand 13 (CXCL13), b2-microglobulin, and kappa free light chain (κ-FLC)." (PMID 40650145, 2025). "The authors found a strong association between the blood levels of CXCL13, sCD23, sCD27, sCD30 and the risk of developing lymphoma." (PMID 41008635, 2025). "Statement of significance: Loss of TFL, found in several types of lymphoma, induces excessive CXCL13 secretion through RNA dysregulation contributing to body weight loss and early death in lymphoma model mice." (PMID 37304286, 2023). "Abnormally high levels of CXCR5 and CXCL13 in the serum of lymphoma patients are significantly associated with poor prognosis." (PMID 33381455, 2020). "Increased CXCL13 levels are detected in plasma and SG from pSS patients, and increased serum CXCL13 concentrations have been correlated with aberrant B cell parameters even associated with lymphoma development." (PMID 33187265, 2020). "Analysis of CXCL13 expression in mucosa-associated lymphoid tissue (MALT) lymphomas shows that the transformed blasts seem to be the major source of the chemokine." (PMID 31354634, 2019). "In NHL, a recent prospective study of inflammatory markers demonstrated a significant association of serum CXCL13 with the risk of lymphoma supporting its role in the lymphoma development." (PMID 25966773, 2015). "Furthermore, high levels of CXCL13 in the serum samples of patients with SjD have been suggested by several studies as a risk factor for the development of lymphoma." (PMID 40650145, 2025). "Moreover, CXCL13 and IL-10 have also been proposed in diagnostic algorithms for the workup of brain lesions in which lymphoma is a possible diagnosis." (PMID 35418930, 2022). "However, as previously reported, we were unable to identify CXCL13 as an independent parameter associated with lymphoma development, a fact that hampers its use as a single molecular biomarker." (PMID 34484201, 2021). "Several clinical studies have demonstrated the potential value of CXCL13 in the early diagnosis of HIV-NHL and have shown significantly elevated serum CXCL13 levels as early as 2.5 years before lymphoma diagnosis." (PMID 40723865, 2025). "The plasma concentration of CXCL13 and other lymphoma-related proteins was assessed with immunochemistry technologies." (PMID 41008635, 2025). "Regarding lymphoma, CXCL13 levels can be very high in B-cell lymphomas, possibly related to production of CXCL13 by malignant B cells." (PMID 39766248, 2024). "In studies on primary Sjogren’s syndrome, CXCL13 and CCL11 have been linked to chronic B-cell activation, disease activity, and the development of lymphoma." (PMID 39451532, 2024). "Since several reports have suggested the association of CXCL13 expression with lymphoma, these findings provide new insights into cytokine regulation via TFL in lymphoma." (PMID 37304286, 2023). "CXCL13 expression in B cell lymphoma is uncommon; however, some reports suggested the association between CXCL-13 expression and lymphoma development." (PMID 37304286, 2023). "Among them, over-expressed CCL18, CCL19, CXCL9, CXCL10, and CXCL13 were listed in the top 20 deregulated genes in all lymphoma datasets." (PMID 35452413, 2022). "Not only do the CXCL13+ and/or CXCR5+ malignant lymphocytes (B cells and Tfh cells) promote the accumulation and proliferation of lymphoma cells, but so do the CXCL13+ FDC and circulating CXCR5+ CD4+ T cells." (PMID 34947813, 2021). "Due to the function of CXCL13 in lymphoma, mounting studies have demonstrated that CXCL13 serves as a useful marker for the diagnosis and prognosis of PCNSL, AITL, MCL, PIOL, and ENKTL." (PMID 34947813, 2021).
lymphoma (continued). "Increased CXCL13 serum levels have been associated with NHL, pSS disease activity and MSG histologic features, whilst in a recent study they were linked to increased lymphoma risk." (PMID 34484201, 2021). "Increased number of infiltrating CXCL13-positive cells was found in severe MSG lesions of pSS patients compared to SSL patients, as well as in high risk pSS patients for lymphoma development." (PMID 34484201, 2021). "Because AITL is derived from TFH cells, CXCL13 was first suggested as a biomarker for this disease, and the 2016 WHO classification of lymphomas included CXCL13 in the diagnostic criteria for AITL." (PMID 31354634, 2019). "The upregulation of CXCL13 has also been demonstrated in H. suis infected mice and has been linked with the development of mucosa associated lymphoid tissue (MALT)-lymphomas in Helicobacter sp." (PMID 28619040, 2017). "Although there is no direct data about the interaction of CXCL13 with CXCR5 in lymphoma cells of ENKTL, a previous in vitro study with AIDS-related non-Hodgkin lymphoma cell lines demonstrated migration of lymphoma cells expressing CXCR5 toward CXCL13." (PMID 25966773, 2015). "The results of the current study thus provide additional evidence that these molecules are overexpressed in AIDS-lymphoma, and that CXCL13 is a potential biomarker for this disease." (PMID 23936541, 2013). "First, in the serum studies, serum CXCL13 levels were significantly elevated prior to lymphoma diagnosis in the AIDS-NHL group, compared to the AIDS control group." (PMID 21490903, 2010). "Specifically, the rs355689 variant in the CXCL13 gene is associated with reduced risk through decreased CXCL13 expression, whereas the rs630923 variant in CXCR5 correlates with increased CXCL13 levels and heightened lymphoma risk." (PMID 40723865, 2025). "On the other hand, CXCL13 could not be used as a specific MS biomarker, as other diseases such as lymphoma and viral meningitis present equal or even higher levels of CXCL13." (PMID 36232832, 2022). "Dysregulated CXCL13 expression is seen in solid tumors including colorectal, breast, prostate, lung, and hepatocellular cancer as well as lymphatic hematological malignancies like lymphoma and CLL." (PMID 36217194, 2022). "Univariate analysis revealed that CXCL13 serum, but not saliva, levels were associated with lymphoma, an association that did not survive multivariate analysis." (PMID 34484201, 2021). "Contrary to the higher lymphoma prevalence along with β2-microglobulin and CXCL13 level in the dryness dominant group observed in the previous study, we could not find any difference in β2-microglobulin level." (PMID 34538269, 2021). "The observed correlation between CXCL13 and these markers may support the role of CXCL13 in lymphoma." (PMID 32047959, 2020). "CXCL13 protein was highly expressed in the CNS lymphoma cells (a‐d)." (PMID 32314548, 2020). "Just as CXCL13 has demonstrated potential clinical utility as a biomarker in infectious diseases involving the CNS, this chemokine has been also proposed as a marker of certain lymphomas." (PMID 31354634, 2019). "CXCR5 and/or CXCL13 expression is elevated in certain carcinomas and lymphomas." (PMID 25271023, 2014). "In other lymphomas, CXCL13 induced chemotaxis of tumor cells." (PMID 23936541, 2013). "Although our findings along with previous studies, indicate that CXCL13 serum levels in pSS patients may associate with high risk to develop NHL, all studies failed to register CXCL13 serum levels as an independent lymphoma predictor." (PMID 34484201, 2021). "Finally, in an attempt to evaluate whether CXCL13 serum levels change upon transition to lymphoma, we estimated its levels in sequential sera of six pSS patients before and at NHL onset." (PMID 34484201, 2021).